USP18 (ubiquitin specific peptidase 18)
Diseases named in the same sentence as USP18 in open-access papers (continued):
Sharing a sentence is not in itself a finding about the gene and the disease.
HIV-1 infection (5 papers, 2019 to 2025). The type species of lentivirus and the etiologic agent of acquired immunodeficiency syndrome (AIDS). "Our study identified a critical role of USP18 in the loss of Mem including HIV-1-specific cells during HIV-1 infection." (PMID 31658294, 2019). "In our recent studies, we demonstrate that HIV-1 infection induces USP18, which dramatically enhances HIV-1 replication by abrogating the antiviral function of p21." (PMID 38675828, 2024). "Human ISG15 and USP18 are also induced by HIV-1 infection, type I IFNs, and genotoxic stress (18, 19, 24, 46, 57, –, 59, 65, 67, 69)." (PMID 31455647, 2019). "Overall, our data show that interfering with USP18 expression during HIV-1 infection leads to better AKT activation in a PTEN-dependent manner." (PMID 31658294, 2019). "Overall, our results show that interfering with PTEN or USP18 during primary HIV-1 infection not only improves Mem survival, but also protects HIV-1-specific cells as well." (PMID 31658294, 2019). "In summary, we show that interfering with USP18 during primary HIV-1 infection protects Mem from apoptosis in a PTEN and AKT-dependent manner and decreases the numbers of apoptotic Mem." (PMID 31658294, 2019). "Here, we found that blocking IFN-I signaling or directly interfering with USP18 expression also led to significant improvements of Mem survival during primary HIV-1 infection." (PMID 31658294, 2019). "Altogether, this study puts USP18/PTEN/AKT at the center of the molecular pathway by which sustained IFN-I signaling leads to Mem impairments during HIV-1 infection." (PMID 31658294, 2019). "To further confirm that USP18 was the ISG responsible for regulating PTEN expression in Mem during HIV-1 infection, we specifically inhibited USP18 expression in Mem using small interfering RNAs (siRNA) silencing." (PMID 31658294, 2019). "In this context, our data reveal that IFNAR blockade in Mem during HIV-1 infection normalized the high expression of the down-stream interferon-induced gene, USP18, in the range of those from uninfected controls." (PMID 31658294, 2019). "Interfering with PTEN activity or specifically with USP18 expression during HIV-1 infection led to significant improvements of Mem survival in an AKT-dependent manner." (PMID 31658294, 2019). "For the validation of the gene expression results and to confirm that the higher expression of these molecules was associated with uncontrolled HIV-1 infection, mRNA levels for PARP9, MX1 and USP18 were validated in independent cohorts of HIV-1 infected individuals." (PMID 32760119, 2020). "To investigate whether higher USP18 expression may regulate PTEN expression in Mem during HIV-1 infection, we first assessed the constitutive ex vivo levels of PTEN in PHI, CHI, ART+ and HIVfree subjects." (PMID 31658294, 2019). "Altogether, we establish a direct role for type I IFN/USP18 signaling in the maintenance of total and virus-specific Mem and provide a new mechanism for the reduced survival of these populations during primary HIV-1 infection." (PMID 31658294, 2019). "This might explain how high USP18 expression in Mem during HIV-1 infection could stabilize PTEN expression and be concomitantly associated with sustained IFN-I signaling." (PMID 31658294, 2019). "This places USP18 as a potential key component of the immune system critical function as it could affect a broad spectrum of cell populations during HIV-1 infection." (PMID 31658294, 2019). "Further experiments are however warranted to know whether we could also counteract CD4 T-cell defective function during HIV-1 infection by specifically interfering with USP18 expression." (PMID 31658294, 2019).
HIV-1 infection (continued). "In addition, while early studies indicated ISG15 deficiency inhibits HIV-1 infection, subsequent mechanistic analyses revealed that this is due to free cellular ISG15 aids the stabilization of the ubiquitin-specific peptidase 18 (USP18), a negative regulator of type I interferon (IFN-I) signaling." (PMID 40568704, 2025). "We found that HIV-1 infection could induce the USP18 protein in myeloid cell lines." (PMID 38675828, 2024). "Therefore, it would be interesting to investigate how USP18 impacts IFN-I signaling regulation during HIV-1 infection, and whether STAT2 and/or IRS-4 are involved." (PMID 31658294, 2019). "Considering the lack of literature surrounding USP18 expression during HIV-1 infection, we next compared its protein levels in the three groups of subjects." (PMID 31658294, 2019). "Therefore, it is not surprising that long-term ART when administrated early during the first months of primary HIV-1 infection was effective in normalizing both IFN-α production and USP18 expression intrinsic to Mem." (PMID 31658294, 2019). "Therefore, we cannot exclude the possibility that longer IFNAR blockade or specific targeting of USP18, which are acting through AKT-dependent mechanisms, might improve cell functions during persistent HIV-1 infection as well." (PMID 31658294, 2019).
leukemia (5 papers, 2016 to 2024). A malignant (clonal) hematologic disorder, involving hematopoietic stem cells and characterized by the presence of primitive or atypical myeloid or lymphoid cells in the bone marrow and the blood. "Taken together, these data suggest that reduced Usp18 expression results in loss of leukemia cells including cells with features of niche resident LSCs, which may be via apoptosis/pyroptosis, activating immune/inflammatory responses." (PMID 36646704, 2023). "Yan and colleagues demonstrated that the removal of UBP43 (also known as USP18) resulted in a reduction in the development of BCR-ABL-induced leukemia." (PMID 39048945, 2024). "The survival of chemotherapy-treated recipients with Usp18+/Δ leukemia cells was significantly prolonged compared to recipients of Usp18+/f cells." (PMID 36646704, 2023). "In the leukemia models, we uncovered that Usp18 has protective role from pyroptosis of leukemia cells including LSC-like population, essential for relapse." (PMID 36646704, 2023). "To explore phenotypic variation upon Usp18 suppression in regulating leukemogenesis, we performed scRNA-seq using GFP+Lin−c-Kit+Usp18+/f and Usp18+/Δ leukemia cells from recipients." (PMID 36646704, 2023). "GFP+ leukemia cells in the PB of Usp18+/f recipients came back earlier than those in Usp18+/Δ recipients, indicating that Usp18 depletion delays relapse after chemotherapy." (PMID 36646704, 2023). "We further validated upregulation of IFN and irradiation responses in GFP+Lin−cKit+ leukemia Usp18+/Δ cells by qRT-PCR and western blots." (PMID 36646704, 2023). "Usp18+/f leukemia cells were transplanted into recipients and Cre was activated after the mice became sick." (PMID 36646704, 2023). "Using an IFNα receptor 1 (IFNAR1) blocking antibody or IgG1 control, we compared leukemia development in Usp18+/f and Usp18+/Δ AE9a recipients." (PMID 36646704, 2023). "We focused on NLRP3 and/or the AIM2 inflammasome because the cluster 9 cells from our scRNA-seq analysis of Usp18+/Δ primary murine leukemia cells predicted inflammasome activation." (PMID 36646704, 2023). "Further studies demonstrated that ectopic ISG15 and USP18 inhibited proliferation of myeloma, leukemia and cervical cancer cells." (PMID 27659523, 2016). "We next examined whether targeting Usp18 can suppress established leukemia, which better represents how a therapy would be applied in a clinical setting." (PMID 36646704, 2023). "Importantly, pathway analyses suggested enhanced pyroptosis/inflammasome activation in Lin−cKit+Usp18+/Δ leukemia cells, supporting our scRNA-seq data." (PMID 36646704, 2023). "Importantly, we also validated the biological effect of Plk2 in WT and Usp18-depleted leukemia cells in vivo." (PMID 36646704, 2023). "Indeed, Usp18+/Δ AE9a leukemia cells were more sensitive to low amounts of type I IFN stimulation than primary bone marrow-derived macrophages (BMDM) in vitro." (PMID 36646704, 2023). "Since PLK2 induced GSDME dependent pyroptosis during USP18 inhibition, we tested whether Plk2 upregulation contributes to the survival benefit of mice transplanted with Usp18 depleted leukemia cell in vivo." (PMID 36646704, 2023). "Since AML levels (GFP) were restored by Plk2 inhibition and the LSC-like population was most reduced by Usp18 depletion in leukemic mice, we hypothesize that Plk2-mediated pyroptosis contributes to LSC reduction in Usp18-depleted leukemia." (PMID 36646704, 2023). "Furthermore, we also detected elevated PLK2 protein levels in Usp18+/Δ leukemia cells compared to Usp18+/f leukemia cells." (PMID 36646704, 2023). "We observed a higher percentage of Annexin V+ cells in GFP+Lin−c-Kit+Usp18+/Δ leukemia cells." (PMID 36646704, 2023). "However, SgPlk2 Usp18+/Δ transplanted mice lost most of the survival benefit obtained from Usp18 inhibition, indicating that Plk2 induction contributes to leukemia cell death during Usp18 depletion in vivo." (PMID 36646704, 2023).
leukemia (continued). "We performed bulk RNA-seq analysis of GFP+Lin−cKit+Usp18+/f and Usp18+/Δ leukemia cells." (PMID 36646704, 2023). "Having demonstrated that heterozygous Usp18 loss does not harm healthy hematopoietic cells, we next tested the effect of heterozygous Usp18 depletion in two well established murine leukemia models since ICD induction by chemotherapy has been shown to effectively kill leukemia cells." (PMID 36646704, 2023). "Finally, to test whether atypical ISG expression can be regulated by similar epigenetic machinery in Usp18 depleted murine leukemia cells in vivo as in the human cell line context, we also performed paired ATAC and RNA-seq using Usp18+/f and Usp18+/Δ murine leukemia cells." (PMID 36646704, 2023). "Originally cloned from leukemia fusion protein AML1-ETO-expressing mice, USP18 is an ISG whose expression level is inducible by type I IFN and is degraded by proteolysis through the SCFSkp2 ubiquitin ligase." (PMID 31871427, 2019). "Consistent with the results in leukemia and myeloma cells, both PARP and caspase-3 were cleaved by ISG15 and USP18 in HeLa cells." (PMID 27659523, 2016). "Just like we observed in our scRNA-seq data of primary leukemia cells, these data demonstrate that lack of USP18 may result in not only apoptosis but also pyroptosis, a form of ICD." (PMID 36646704, 2023).
lupus (5 papers, 2022 to 2025). "For example, using HERC5 gene expression in lymphoblastoid cell lines as a readout of the missense variant effect on USP18 protein function allowed us to establish a potentially causal link between reduced USP18 function and increased lupus risk." (PMID 41004399, 2025). "Here the authors perform a trans expression quantitative trait locus meta-analysis study of over 3,700 people and link a USP18 variant to expression of 50 inflammation genes and lupus risk, highlighting how genetic regulation of immune responses drives autoimmune disease and informs new therapies." (PMID 41038828, 2025). "Similarly, we have used downstream effects of genetic variation on gene expression (trans-eQTLs) to characterize the impact of a lupus-associated USP18 missense variant on its protein function." (PMID 41004399, 2025). "To further characterise the potential role of USP18 target genes in lupus, we performed additional trans-eQTL meta-analysis across the nine discovery cohorts and one replication cohort (total n = 4416)." (PMID 41038828, 2025). "This revealed that three prioritised lupus genes (USP18, STAT1, IFNA1-17) were shared with the 13 category I genes (IFNAR1/2 signal transduction proteins) and four prioritised genes (IRF1/5/8 and OAS1) were shared with the 38 category II genes (transcriptional targets of interferon response)." (PMID 41038828, 2025). "The trans-eQTL signal at the ubiquitin specific peptidase 18 (USP18) locus colocalised with a GWAS signal for systemic lupus erythematosus (SLE)." (PMID 41038828, 2025).
Aicardi-Goutières syndrome (4 papers, 2021 to 2023). "We next examined baseline gene expression (qPCR) of archetypal interferon stimulated genes (ISGs) IFI27, USP18, MX1, OASL, IRF7, and MX2, and those ISGs found highly expressed in PBMCs from the type 1 interferonopathy, Aicardi-Goutières syndrome (AGS) patients (IFI27, ISG15, IFI44L, and RSAD2)." (PMID 33746960, 2021).
glioma (4 papers, 2021 to 2025). A benign or malignant brain and spinal cord tumor that arises from glial cells (astrocytes, oligodendrocytes, ependymal cells). "Therefore, proteins associated with glioma stemness are more likely to be targeted and regulated by USP18, especially SOX9, because of its widely recognised role in promoting GSCs." (PMID 40374599, 2025). "However, to date, the specific upstream and downstream molecular mechanisms underlying the oncogenic effects of USP18, particularly its role in promoting glioma stemness, remain largely unexplored." (PMID 40374599, 2025). "In the TCGA database, we observed that USP18 expression levels were significantly higher in IDH-wild-type gliomas than in IDH-mutant gliomas." (PMID 40374599, 2025). "The results from the EdU and Transwell assays further confirmed that YY1 can promote the proliferation, invasion, and migration abilities of glioma cells by regulating USP18." (PMID 40374599, 2025). "To further validate the clinical relevance of this regulation, we analyzed SOX9 protein expression by immunohistochemistry in 90 human glioma specimens and correlated its expression with USP18 IHC scores." (PMID 40374599, 2025). "Box plots revealed a positive correlation between USP18 transcript levels and increasing glioma grade." (PMID 40374599, 2025). "Given the significant impact of USP18 on glioma cells, identifying the upstream transcription factors responsible for its regulation is crucial." (PMID 40374599, 2025). "To further investigate the impact of USP18/SOX9 on glioma progression, we established orthotopic xenograft models." (PMID 40374599, 2025). "In this study, we detected high expression levels of USP18 in glioma cells, particularly in glioma stem cell subpopulations, and found that its expression was correlated with patient prognosis." (PMID 40374599, 2025). "We found that USP18 expression was significantly higher in glioma tissues than in normal brain tissues, with levels further increasing with increasing WHO grade." (PMID 40374599, 2025). "Next, we investigated the protein levels of USP18 using Western blot analysis in freshly collected glioma tissues and normal brain tissues (NBTs) obtained from decompressive craniectomy for nontumor indications." (PMID 40374599, 2025). "We also examined both the mRNA and protein expression levels of USP18 in various glioma cell lines and two human astrocyte cell lines." (PMID 40374599, 2025). "After determining the biological functions of USP18 in glioma, we explored the potential regulatory mechanisms involved." (PMID 40374599, 2025). "Through a series of in vitro and in vivo experiments, we further confirmed that USP18 promotes glioma cell proliferation, invasion, and migration." (PMID 40374599, 2025). "Given that glioma grade is a significant prognostic factor, we further explored the expression of USP18 across different WHO grades (II–IV)." (PMID 40374599, 2025). "We further investigated USP18 expression levels across different molecular subtypes of glioma using the TCGA and CGGA databases." (PMID 40374599, 2025). "We observed greater expression of USP18 to varying degrees in glioma cell lines than in human astrocyte cells." (PMID 40374599, 2025). "By analyzing the expression levels of DUBs and their correlation with GALM in gliomas, combined with in vitro experiments, four DUBs were selected, namely, USP18, TNFAIP3, USP39, and USP38." (PMID 35127693, 2021). "Next, we investigated the impact of YY1 on glioma stemness and the role of USP18 in this context." (PMID 40374599, 2025). "To confirm whether SOX9 mediates the biological functions of USP18 in glioma cells, we conducted a series of rescue experiments." (PMID 40374599, 2025). "In the current study, we demonstrated the positive role of USP18 in promoting glioma stemness." (PMID 40374599, 2025). "Following puromycin selection, we established stable USP18-knockdown glioma cell lines." (PMID 40374599, 2025).
glioma (continued). "Notably, SOX9 and USP18 protein levels exhibited a statistically significant positive correlation in glioma tissues." (PMID 40374599, 2025). "Additionally, through analysis of multiple glioma GEO public sequencing datasets, we observed a significant increase in USP18 expression in glioma tissues compared with normal brain tissues." (PMID 40374599, 2025). "Additionally, analysis of proteomics data from the Clinical Proteomic Tumour Analysis Consortium (CPTAC) confirmed that SOX9 protein expression in glioma tissue is significantly higher than that in normal brain tissue, and this pattern is consistent with the changes observed for USP18 expression." (PMID 40374599, 2025). "Additionally, studies on the role of USP18 in gliomas are rare." (PMID 40374599, 2025). "Immunofluorescence experiments further confirmed the colocalization of the USP18 protein and the SOX9 protein in glioma cells." (PMID 40374599, 2025). "Bioinformatics analysis also revealed a positive correlation between the expression levels of USP18 and YY1 across multiple glioma public databases." (PMID 40374599, 2025). "We analysed glioma single-cell data from 15 project sources in the TISCH database and found that USP18 was expressed predominantly in cancer cells." (PMID 40374599, 2025). "In this study, we identified a member of the DUB family, USP18, which regulates the protein stability of SOX9, thereby promoting the maintenance of glioma stemness and tumour progression." (PMID 40374599, 2025). "Additionally, gliomas with 1p/19q codeletion presented significantly higher USP18 expression levels than those without 1p/19q codeletion across all datasets (TCGA, CGGA693 and CGGA325)." (PMID 40374599, 2025).
Salmonella Infections (4 papers, 2014 to 2021). Infections with bacteria of the genus SALMONELLA. "A mutation in USP18 leads to an increased bacterial load in spleen and liver in mice, and it is also associated with an altered inflammatory response to Salmonella infection, e.g., increase in Type 1 IFN or IL-6 secretion, but a decrease in STAT4 phosphorylation and IFN-γ production." (PMID 25505465, 2014). "During systemic Salmonella infection, increased STAT1 activation correlated with impaired STAT4 activation and reduced IFN-γ production, and Usp18 mutant mice are more susceptible to systemic (i.e., typhoid) S. Typhimurium infection." (PMID 28352268, 2017). "The majority of these genes were chemokines, cytokines, and other immune related genes with a significant number of genes regulated by Type I and Type II IFN including several members of the Gbp family, Stat1, Usp18 as well as others that are known to be involved in Salmonella infection." (PMID 25161653, 2014).
Type 1 interferonopathies (4 papers, 2021 to 2024). "Two studies observe that humans or mice with the deletion of USP18 are prone to have type 1 interferonopathy, leading to severe pseudo-TORCH syndrome or destructive brain interferonopathy." (PMID 34016972, 2021).
bladder (3 papers, 2019 to 2024). "Serum USP18 concentrations were the highest in healthy individuals and kidney transplant recipients." (PMID 38791035, 2024).